ROR1 (ROR family WNT receptor 1)
Diseases named in the same sentence as ROR1 in open-access papers (continued):
Sharing a sentence is not in itself a finding about the gene and the disease.
sarcoma (continued). "IGF1R and ROR1 CAR T cells derived from eight healthy donors using the Sleeping Beauty (SB) transposon system were cytotoxic against sarcoma cells and produced high levels of IFN-γ, TNF-α and IL-13 in an antigen-specific manner." (PMID 26173023, 2015). "Here, we report that IGF1R (15/15) and ROR1 (11/15) were highly expressed in sarcoma cell lines including Ewing sarcoma, osteosarcoma, alveolar or embryonal rhabdomyosarcoma, and fibrosarcoma." (PMID 26173023, 2015). "IGF1R and ROR1 CAR T cells generated from three sarcoma patients released significant amounts of IFN-γ in response to sarcoma stimulation." (PMID 26173023, 2015). "Infusion of IGF1R and ROR1 CAR T cells also prolonged animal survival in a localized sarcoma model using NOD/scid mice." (PMID 26173023, 2015). "Our results support future clinical trials in high risk sarcomas using SB modified CAR T cells targeting IGF1R and ROR1." (PMID 26173023, 2015). "Our preclinical data suggest that IGF1R CAR T cells mounted more potent anti-sarcoma activity than ROR1 CAR T cells in vivo." (PMID 26173023, 2015). "IGF1R CAR T cells produced higher amounts of IL-6 and IL-18 than ROR1 CAR T cells in response to certain sarcoma lines." (PMID 26173023, 2015). "Several other targets of interest such as insulin-like growth factor receptor 1 (IGF-1R), receptor tyrosine kinase-like orphan receptor 1 (ROR1), and Ephrin type-A receptor 2 (EphA2) are overexpressed in various sarcomas and few CAR T-cell therapy clinical studies are currently ongoing." (PMID 40940995, 2025). "Furthermore, the in vitro and in vivo anti-sarcoma activity of ROR1-targeted CAR-T cells were indicated." (PMID 34566963, 2021). "Several papers have established the involvement of EGFR in ROR1-mediated survival signaling within carcinomas, which may not be able to explain why ROR1 is expressed the highest in the sarcoma and mesothelioma and predicts bad prognosis in these cancers." (PMID 31137681, 2019). "Here, we investigated CAR T-cell therapy targeting IGF1R and ROR1 in sarcomas." (PMID 26173023, 2015). "Our data indicate that both IGF1R and ROR1 can be effectively targeted by SB modified CAR T cells and that such CAR T cells may be useful in the treatment of high risk sarcoma patients." (PMID 26173023, 2015). "This experiment prompted us to examine ROR1 expression in sarcoma lines." (PMID 26173023, 2015). "Significant anti-sarcoma activity was evident at days 14 and 21 by ROR1 CAR T cells (p < 0.01)." (PMID 26173023, 2015). "Moreover, adoptive transfer of IGF1R and ROR1 CAR T cells also demonstrated a prolonged survival benefit in a localized sarcoma model." (PMID 26173023, 2015). "IGF1R and ROR1 CAR T cells may represent a new treatment option for patients with metastatic or relapsed/refractory sarcomas." (PMID 26173023, 2015). "We also evaluated ROR1 CAR T cell cytotoxicity against sarcoma cells using 51Cr-release assays." (PMID 26173023, 2015). "Thus, ROR1 CAR T-cell therapy in sarcomas may yield an effective treatment with minimal off-target toxicity." (PMID 26173023, 2015). "Other promising preclinical results with CAR-T cells have been achieved by targeting IGF1R and receptor tyrosine kinase-like orphan receptor 1 (ROR1), both of which are expressed across many sarcoma cell lines, including RMS." (PMID 41007114, 2025). "These ROR1 CAR-T cells were effective against sarcoma cells as evidenced by the synthesis of high levels of IFN-γ, TNF-α, and IL-13 in cocultures with sarcoma cell lines and the ability to reduce the tumor growth in a murine osteosarcoma xenograft model." (PMID 36873868, 2023). "The highest ROR1 expressers include mesothelioma (MESO), sarcoma (SARC), stomach adenocarcinoma (STAD), ovarian cystadenocarcinoma (OV), and pancreatic adenocarcinoma (PAAD)." (PMID 31137681, 2019). "In conclusion, our results have demonstrated in vitro and in vivo anti-sarcoma activity of IGF1R and ROR1 CAR T cells." (PMID 26173023, 2015).
sarcoma (continued). "Similar levels of IGF1R or ROR1 CAR and GFP coexpression were observed in nucleofected PBMCs from two healthy donors and two sarcoma patients compared to SB modified T cells co-expressing CD19 CARs and CD20 as we previously reported (data not shown)." (PMID 26173023, 2015). "The transduced sarcoma lines were recognized as efficiently as the parent lines by patient 1 IGF1R and ROR1 CAR T cells." (PMID 26173023, 2015). "Second, SB modified CAR T cells derived from healthy donors and sarcoma patients targeting IGF1R or ROR1 displayed a specific cytotoxicity and released predominantly IFN-γ, TNF-α and IL-13 cytokines against sarcomas in vitro." (PMID 26173023, 2015). "We employed a time-dynamic bioluminescent imaging (BLI) technique in live mice to assess the anti-sarcoma effect of SB-engineered IGF1R and ROR1 CAR T cells." (PMID 26173023, 2015). "Furthermore, the scientists discovered that IGF1R or ROR1 CAR-T cells were highly effective at inhibiting the growth of sarcoma in localized and disseminated sarcoma xenograft models which resulted in a prolonged survival rate." (PMID 36983330, 2023). "In addition, their studies indicated that ROR1-targeted CAR-T cells showed specific cytotoxicity and released mainly IFN-γ, TNF-α, and IL-13 cytokines against sarcomas in vitro." (PMID 34503279, 2021). "First, ROR1 is expressed in many types of sarcoma including EWS, OS and RMS, suggesting that ROR1 could be used as a therapeutic target in sarcomas." (PMID 26173023, 2015). "Mock T cells or CAR T cells co-cultured with ROR1- K562 cells did not release cytokines whereas IGF1R CAR T cells co-cultured with IGF1R+/- K562 cells produced a low level of cytokines compared to IGF1R+ sarcomas." (PMID 26173023, 2015). "In addition, both IGF1R and ROR1 CAR T cells but not mock T cells derived from 3 patients with sarcoma released significant amounts of IFN-γ in response to specific sarcoma antigen stimulation." (PMID 26173023, 2015). "Importantly, ROR1 may act as a survival factor for sarcoma cells although its function in sarcoma is not known." (PMID 26173023, 2015). "Co-culture of PBMCs with IGF1R and ROR1 CAR T cells derived from a sarcoma patient and a healthy donor revealed a low level of recognition of PBMCs by IGF1R CAR T cells but not ROR1 CAR T cells compared to sarcoma cells." (PMID 26173023, 2015).
acute lymphoblastic leukemia (14 papers, 2012 to 2025). Leukemia with an acute onset, characterized by the presence of lymphoblasts in the bone marrow and the peripheral blood. "Beyond CLL, ROR1 has been implicated in other hematologic malignancies, including acute lymphoblastic leukemia (ALL), non-Hodgkin lymphomas (NHLs), and myeloid malignancies." (PMID 41479906, 2025). "UHRF1 regulates and maintains the levels of ROR1 and is required for the viability of lymphoblastic leukemia through a mechanism associated with ROR1 expression." (PMID 37630248, 2023). "The inhibition of UHRF1 in combination with desatinib leads to a decrease in the ROR1 levels, suggesting a novel mechanism to target acute lymphoblastic leukemia." (PMID 37630248, 2023). "The expression of ROR1 is crucial for the survival of acute lymphoblastic leukemia, chronic lymphocytic leukemia, and various solid cancers." (PMID 37630248, 2023). "ROR1 has been shown to crosstalk with the B‐cell receptor (BCR) through the BCR complex and Bruton's tyrosine kinase (BTK) as well as with associated signaling molecules in acute lymphoblastic leukemia (ALL) B cells." (PMID 35844694, 2021).
diffuse large B-cell lymphoma (13 papers, 2014 to 2025). "Zilovertamab vedotin (ZV) is an antibody–drug conjugate targeting ROR1, which is being evaluated in diffuse large B-cell lymphoma (DLBCL)." (PMID 40805213, 2025). "Zilovertamab vedotin, an antibody–drug conjugate (ADC) targeting ROR1, demonstrated response rates of 47% and 60% in mantle cell and diffuse large B-cell lymphomas, respectively." (PMID 40723210, 2025). "In this study, we explored clinical and functional inhibitory aspects of ROR1 in diffuse large B-cell lymphoma (DLBCL)." (PMID 32586008, 2020). "ROR1 expression showed a significant prognostic factor in patients with CLL, and several studies identified aberrant expression of ROR1 in other hematologic malignancies, diffuse large B cell lymphoma, follicular lymphoma, and marginal zone lymphoma." (PMID 37241228, 2023). "Studies found that several other types of non-Hodgkin lymphoma (NHL), including diffuse large B cell lymphoma (DLBCL), follicular lymphoma, and marginal zone lymphoma expressed ROR1, but its function was not clearly characterized." (PMID 34123850, 2021).
glioblastoma (13 papers, 2017 to 2026). The most malignant astrocytic tumor (WHO grade IV). "In another study, an in vitro and in vivo evaluation of the possibility and effectiveness of combining a C021 oncolytic virus, which targets ROR1-positive glioblastoma cells and activates IL-21 secretion in them, with anti-ROR1-CAR-NK cells was carried out." (PMID 41369346, 2025). "ROR1 is overexpressed in glioblastomas and is preferentially expressed within 448 and X01 glioblastoma stem cells (GSCs) compared to total cell populations." (PMID 40869147, 2025). "ROR1 plays a role in maintaining the stemness of these glioblastoma stem cells, and its expression can be enhanced by signaling pathways active in the CSC niche, such as Notch signaling and hypoxia pathways." (PMID 40869147, 2025). "Other histologic types such as breast, lung, renal cell, hepatocellular, urothelial carcinoma, and colon carcinomas; glioblastoma; cholangiocarcinoma; and leiomyosarcoma showed less ROR1 overall expression, ranging between 0.9 and 13%." (PMID 38791952, 2024). "Therefore, ROR1 is a key driver of CSC characteristics in glioblastoma through cross-signaling networks, making it an attractive therapeutic target to overcome CSC-mediated tumor progression and resistance in glioblastoma." (PMID 40869147, 2025). "Therapeutically, targeting ROR1 via endothelial-specific Adno-Associated Virus (AAV) knockdown or the antibody-drug conjugate Zilovertamab vedotin (VLS-101) normalizes vasculature, improves temozolomide delivery, and sensitizes tumors in glioblastoma organoids and xenografts." (PMID 41562250, 2026). "The ROR1 inhibitor Strictinin, an ellagitannin isolated from Myrothamnus flabellifolius, has demonstrated inhibitory effects on the spheroid-forming capacity of T98G glioblastoma stem-like cells, suggesting its potential in treating this aggressive brain cancer." (PMID 40869147, 2025). "For instance, in glioblastoma, IGFBP5 can promote tumor invasion through the ROR1/HER2-CREB signaling pathway." (PMID 41282023, 2025). "ROR1 functions by activating several downstream signaling pathways crucial for CSC maintenance and aggressiveness in glioblastoma CSCs." (PMID 40869147, 2025). "Clinically, high ROR1 and WNT5A expression correlates with poor glioblastoma prognosis, and WNT5A may serve as a circulating biomarker." (PMID 41562250, 2026). "Moreover, in glioblastoma, the binding of insulin-like growth factor-binding protein 5 (IGFBP5) to ROR1 facilitates the formation of a ROR1/HER2 heterodimer, which subsequently induces the expression of genes like ETV5 and FBXW9 to promote glioblastoma stem-like cell invasion and tumorigenesis." (PMID 40869147, 2025). "Interestingly, the pseudokinase RTKs PTK7, ROR1, and ROR2 that activate the Wnt pathway rather than the canonical MAPK and PI3K pathways were mildly to moderately overexpressed in all glioblastoma subgroups." (PMID 34572759, 2021).
non-small cell lung carcinoma (13 papers, 2015 to 2025). A group of at least three distinct histological types of lung cancer, including non-small cell squamous cell carcinoma, adenocarcinoma, and large cell carcinoma. "It targets an antigen called ROR1, which is overexpressed in several solid tumor types, including non small cell lung cancer (NSCLC) and triple-negative breast cancer (TNBC)." (PMID 39408696, 2024). "ROR1 silencing in non-small cell lung cancer (NSCLC) cell lines led to decreased activity of the PI3K/AKT/mTOR signaling pathway, which is related to apoptosis and antiproliferative effects on tumor cells." (PMID 36873868, 2023). "ROR1 expression was found to occur significantly more often in female than in male non-small cell lung cancer patients (p = 0.048)." (PMID 25978653, 2015). "The combination of αmPD-1 mAb with ROR1 DAC enhanced the suppression of tumor growth compared to ROR1 DAC monotherapy, consistent with studies of JQ1 and PD-1 mAb combinations in non-small cell lung cancer." (PMID 39816690, 2025). "Treatment with ARI-1 blocked downstream ROR1 signaling via PI3K/AKT/mTOR, thus inhibiting proliferation and migration of ROR1-positive non-small cell lung cancer cells in vitro and in vivo." (PMID 33445713, 2021).
osteosarcoma (13 papers, 2015 to 2025). A usually aggressive malignant bone-forming mesenchymal neoplasm, predominantly affecting adolescents and young adults. "In osteosarcoma, ROR1 dimerizes with ROR2 to activate WNT5A/RHOA/DAAM1 signaling in parallel with PI3Ka/AKT to regulate migration and cytoskeletal rearrangement in MG63 and U2OS cells." (PMID 40869147, 2025). "Further experiments focusing on the role of additional WNT ligands and the role of ROR1 in maintaining CSCs are an important next step for patients with osteosarcoma." (PMID 40869147, 2025). "In vitro, the derivative of Zilovertamab, D10, inhibited sphere formation, increased methotrexate sensitivity and reduced expression of SOX2 demonstrating the role of ROR1 in osteosarcoma CSCs and chemoresistance." (PMID 40869147, 2025). "Future studies should test the inhibition of ROR1 in WNT5B-expressing osteosarcomas in vivo using Zilovertamab or a similar drug." (PMID 39102216, 2024). "ROR1 CAR T cells also showed effectiveness in high risk sarcoma xenograft models (e.g., Ewing sarcoma, osteosarcoma, rhabdomyosarcoma)." (PMID 33445713, 2021). "Furthermore, ROR1 has been shown to express with WNT5B to regulate osteosarcoma stemness in 143B, MG63 and patient-derived xenografts." (PMID 40869147, 2025). "Interestingly, ROR1 or ROR2 upregulation has been observed in many cancers: ROR1 is upregulated in solid tumors or hematologic malignancies while ROR2 is overexpressed in osteosarcomas or renal cell carcinomas." (PMID 35295854, 2022). "Currently, potential effective targets for CAR-T cell therapy in osteosarcoma include HER2, IGF1R, ROR1, EphA2, CSPG4, folate receptor with EC17, B7-H3, GD2, NKG2D, ALCAM/CD166, IL-11Rα, and FAP." (PMID 38187386, 2023). "Similar to ROR1, ROR2 supported proliferation and tumor growth, while inhibiting apoptosis both in vitro as well as in vivo in mouse models of osteosarcoma, breast and renal cancer." (PMID 33445713, 2021). "Anti-receptor tyrosine kinase-like orphan receptor 1 (ROR1) CAR-NK cells also demonstrated significantly enhanced cytotoxicity in vitro against EWS and osteosarcoma cell lines compared to mock expanded NK cells." (PMID 34804076, 2021). "Thus, IGF1R and tyrosine kinase-like orphan receptor 1 (ROR1) CAR-T cells obtained from sarcoma patients could secrete Inf-γ and pronouncedly attenuate tumor growth in systemically disseminated and localized osteosarcoma xenograft mouse models." (PMID 34069554, 2021).
gastric cancer (11 papers, 2015 to 2023). A primary or metastatic malignant neoplasm involving the stomach. "The increased protein level of phosphorylation c-Src (p-c-Src) in gastric cancer cell caused by ROR1 was identified in this study." (PMID 26576539, 2015). "However, the clinical potentials and underlying mechanisms of ROR1 in gastric cancer progression remain largely unknown." (PMID 26576539, 2015). "An association between ROR1, phosphorylated CREB and AKT was also observed by IHC in human gastric cancer patients." (PMID 33445713, 2021). "Enough evidence demonstrates that miR-27b, like miRNA, can suppress the proliferation of gastric cancer by targeting ROR1." (PMID 27844448, 2017). "Furthermore, we identified STAT3 as a downstream ROR1 target in OC cells, which is in line with previous findings in ROR1+ leukemic cells and gastric cancer." (PMID 37400436, 2023). "Molecularly, a previous study also highlighted that miR-27b-3p could activate cell proliferation, regulate colony formation and promote tumorigenicity by targeting ROR1 in gastric cancer cells." (PMID 29212222, 2017). "MiR-27b-3p suppressed cell proliferation through targeting ROR1 in gastric cancer." (PMID 27655675, 2016). "The expression patterns of miR-27b-3p and ROR1 in human gastric cancer (GC) specimens and cell lines were determined by microRNA RT-PCR and western blotting." (PMID 26576539, 2015).